C1RL (complement C1r subcomponent like)
Description:
Mediates the proteolytic cleavage of HP/haptoglobin in the endoplasmic reticulum.
Synonyms: C1r-LP; CLSPa; C1RL1; C1RLP
Tractability: Antibody: UniProt places it where antibodies can reach, with high confidence; UniProt predicts a signal peptide or a membrane-spanning region; its Gene Ontology location is reachable by antibodies, with medium confidence. PROTAC: its protein half-life has been measured.
Gene: Protein-coding gene on chromosome 12 (7,089,587 to 7,109,245, reverse strand). Ensembl gene ENSG00000139178.
Subcellular location: Secreted
Gene Ontology:
Molecular function: serine-type endopeptidase activity
Biological process: zymogen activation; proteolysis
Cellular component: extracellular exosome; extracellular region; blood microparticle
Genetic constraint (gnomAD): Loss-of-function variants: 30 observed, 33.77 expected, observed/expected ratio (o/e) 0.89, 90% interval 0.66 to 1.21. The upper end of that interval is the gene's LOEUF score, 1.21, which puts it in group 5 of 6, group 1 being the genes least tolerant of losing a copy. Missense variants: 563 observed, 642.97 expected, observed/expected ratio (o/e) 0.88, 90% interval 0.82 to 0.94. Synonymous variants: 248 observed, 258.61 expected, observed/expected ratio (o/e) 0.96, 90% interval 0.86 to 1.07.
Homologues: Orthologues: chimpanzee C1RL (99% identical), macaque C1RL (94% identical), dog C1RL (75% identical), guinea pig C1RL (75% identical), pig C1RL (73% identical), mouse C1rl (73% identical), rat C1rl (72% identical), zebrafish f9a (20% identical), tropical clawed frog cfi (18% identical), zebrafish habp2 (17% identical), Drosophila melanogaster CG31266 (13% identical), Drosophila melanogaster CG31267 (11% identical). Paralogues in human: C1R (51% identical), C1S (31% identical), F9 (20% identical), F10 (20% identical), HGFAC (19% identical), HPR (19% identical), F11 (18% identical), F12 (18% identical), HP (18% identical), KLKB1 (18% identical), CFI (17% identical), F7 (17% identical), and 4 more.
Diseases named in the same sentence as C1RL in open-access papers:
C1RL is named in the same sentence as 19 diseases in open-access papers, as found by Europe PMC text mining. Sharing a sentence is not in itself a finding about the gene and the disease. The quoted sentences say what the papers report.
endometrial cancer (4 papers, 2021 to 2024). Primary or metastatic malignant neoplasm involving the endometrium (mucous membrane that lines the endometrial cavity). "The observation of enhanced levels of clusterin, ITIH4, antithrombin-III, and C1RL in sera of endometrial cancer patients allowed a mathematical model to be built to detect cancer samples." (PMID 36232415, 2022). "Quantification of protein expression revealed the upregulation of CLU, ITIH4, SERPINC1, and C1RL in endometrial cancer samples compared to the sera of control subjects." (PMID 34298850, 2021). "Six of them were upregulated in endometrial cancer patients (CLU, SERPINC1, ITIH4, C1RL, APOC3 and DSC1), while ten were downregulated (APCS, C9, APOA1, ALB, APOA4, CFHR1, ITIH2, and ACTB)." (PMID 39194522, 2024).
glioblastoma (3 papers, 2020 to 2023). The most malignant astrocytic tumor (WHO grade IV). "C1RL was previously found to be involved in immunological activities and reported as an independent prognostic biomarker in glioblastoma (GBM); interestingly, C1RL was also found to be upregulated (in GBM) in the study." (PMID 36979356, 2023). "We found that C1RL expression was upregulated in glioblastoma (GBM), especially mesenchymal GBM and primary GBM." (PMID 32993564, 2020). "Although OGFOD1, C1RL, CD81, and ITPKC play pivotal roles in several cancers, their involvement in glioblastoma remains undocumented." (PMID 35936722, 2022). "Furthermore, the CNV of all model genes, except C1RL, could influence certain immune cell infiltration levels in glioblastoma, and only dendritic cell infiltration levels affected the survival rate of glioblastoma patients." (PMID 35936722, 2022).
COVID-19 (2 papers, 2022 to 2025). A disease caused by infection with severe acute respiratory syndrome coronavirus 2. "C1RL is a component of the classical complement pathway, although its specific role in COVID-19 remains poorly characterized." (PMID 40821834, 2025). "However, radar plots revealed a clear decrease in the average abundance of several complement proteins in IVIG-treated patients compared to both COVID-19 controls and healthy donors, including C1RL, CFD, CD5L, C8G, and CFHR5." (PMID 40821834, 2025). "In the complement pathway, IVIG treatment decreased levels of C1RL, C8G, and CFD compared to COVID-19 controls." (PMID 40821834, 2025).
glioma (2 papers, 2020 to 2023). A benign or malignant brain and spinal cord tumor that arises from glial cells (astrocytes, oligodendrocytes, ependymal cells). "C1RL-associated genes were defined as genes with expression trends similar to those of C1RL in glioma samples." (PMID 32993564, 2020). "Increased C1RL expression accompanied the IDH1-wt phenotype in both lower grade glioma (LGG) and GBM." (PMID 32993564, 2020). "Our results imply that C1RL is involved in immunological activities and is an independent unfavourable prognostic biomarker in patients with glioma." (PMID 32993564, 2020). "Our results showed evidence that C1RL is highly expressed in glioma samples and predicts a poor prognosis." (PMID 32993564, 2020). "Through analysis of 2120 glioma patients from 5 public datasets, the relationships between C1RL expression and clinicopathological characteristics were evaluated." (PMID 32993564, 2020). "The patients with glioma exhibiting higher C1RL expression had significantly shorter survival times than their counterparts in the GSE16011mic, TCGAseq, CGGAmic, and CGGAseq datasets." (PMID 32993564, 2020). "Higher C1RL expression predicted unfavourable survival in patients with glioma and therapeutic resistance in GBM." (PMID 32993564, 2020). "Given that CD86, LGALS9, and TGFB1 play immunosuppressive roles in glioma, we further investigated the expressing relationship between C1RL and these immunosuppressive genes." (PMID 32993564, 2020). "Increased amounts of immune cells, especially M2 macrophages, migrated into glioma tumours with relatively high C1RL expression." (PMID 32993564, 2020). "Secondary GBM was developed from lower grade glioma and exhibited lower C1RL expression than primary GBM." (PMID 32993564, 2020). "Overall, our results indicate that C1RL is a biomarker of poor outcomes in glioma patients." (PMID 32993564, 2020). "C1RL is a potential clinical immunotherapeutic target for glioma treatment in the future." (PMID 32993564, 2020). "Due to the distinct outcomes of the glioma subgroups, the differences in C1RL expression in different histopathological subgroups may contribute to the observed differences in survival." (PMID 32993564, 2020). "All these results are consistent with the hypothesis that C1RL palys an immunosuppressive role in glioma." (PMID 32993564, 2020). "C1RL may trigger the classical complement pathway by activating C1s and thus contribute to the pathogenesis of glioma." (PMID 32993564, 2020). "C1RL probably plays an important role in glioma immunosuppression." (PMID 32993564, 2020). "Furthermore, C1RL probably plays an immunosuppressive role in the pathogenesis of glioma by triggering the activation of haptoglobin and C1s." (PMID 32993564, 2020). "In the present study, we employed 2120 glioma specimens and 23 non-tumour brain tissues from 5 datasets to explore the clinicopathological and biological characteristics of C1RL in glioma." (PMID 32993564, 2020). "The results indicate that C1RL is a negative biomarker for the patients with glioma." (PMID 32993564, 2020).
breast carcinoma (1 paper, 2024). "In Tamoxifen-treated MCF7 samples, the downregulation of the JCHAIN and C1RL, which are reported by the Human Protein Atlas database to be associated with favourable outcomes in breast cancer, is of concern; however, IGKV-4, which is favourable in breast cancer, was upregulated." (PMID 38233507, 2024).
depression (1 paper, 2022). "In our study, two proteins involved in complement activation, namely FHR1 and C1RL, were selected by EN for the individuals with depression and dysphoria." (PMID 35326481, 2022).
diffuse large B-cell lymphoma (1 paper, 2020). "A gene-based analysis showed significant associations between non-Hodgkin lymphoma or diffuse large B-cell lymphoma and the C1RL gene." (PMID 32993564, 2020). "C1RL had not been mentioned in cancer until a report indicating significant associations of non-Hodgkin lymphoma and diffuse large B-cell lymphoma with the C1RL gene in 2012." (PMID 32993564, 2020).
hepatocellular carcinoma (1 paper, 2020). A malignant tumor that arises from hepatocytes. "Complement C1r subcomponent like (C1RL) was found to be a prognostic marker in hepatocellular carcinoma and renal cell cancer." (PMID 32993564, 2020). "In recent years, C1RL has been reported to be a prognostic biomarker in hepatocellular carcinoma and renal cell cancer." (PMID 32993564, 2020).
melanoma (1 paper, 2023). A malignant, usually aggressive tumor composed of atypical, neoplastic melanocytes. "In our experiments in vitro, we found the melanoma cell lines of C1RL overexpression grew more slowly and reduced migratory capacity." (PMID 37227816, 2023). "We further investigate the protein level of C1RL in melanoma cell lines." (PMID 37227816, 2023). "Notably, we also found that C1RL protein may inhibit the growth of melanoma cell lines." (PMID 37227816, 2023).
Obesity (1 paper, 2019). Accumulation of substantial excess body fat. "In the current study, we found that C1RL, C6, and C8G plasma levels were significantly lower in the CRPS group compared with the CR group, which suggests that CRPS reduces inflammatory responses in people with obesity." (PMID 30736312, 2019).
cancer (6 papers, 2012 to 2023). A tumor composed of atypical neoplastic, often pleomorphic cells that invade other tissues. "Similarly, of the genes associated with CIN3/cancer, C1RL, GDF10, and GDF2 were also associated with persistence (p-values of 0.00875, 0.0423, and 0.04080, respectively)." (PMID 22496757, 2012). "Western blotting data analysis confirmed the upregulation of CLU, ITIH4, SERPINC1, and C1RL in endometrial and exosome cancer sera compared to those of control subjects." (PMID 34298850, 2021). "The 10-biomarker signature in this category additionally incorporating FABP5, C1RL, MMP9, ECM1, S100A7 and CF1, discriminated early-stage cancers from controls with an AUC of 0.92 (0.86–0.97)." (PMID 36807337, 2023).
tumor (3 papers, 2020 to 2023). "C1RL expression was also correlated with reduced tumor purity and increased M2 macrophage infiltration." (PMID 35488886, 2022). "C1RL expression was also correlated with reduced tumour purity and increased M2 macrophage infiltration." (PMID 32993564, 2020). "Complement C1r subcomponent like (C1RL), a prognostic biomarker in several kinds of tumours, has attracted increasing attention from oncologists." (PMID 32993564, 2020). "In addition, tumour purity, leukocyte infiltration and overall survival were evaluated based on C1RL expression." (PMID 32993564, 2020). "In addition, tumour purity showed an inverse correlation with C1RL expression trends." (PMID 32993564, 2020). "But we still unsure whether C1RL promotes anti-tumour immune response or suppress it." (PMID 32993564, 2020). "The biological function of C1RL, especially in tumours, has not been clarified thoroughly." (PMID 32993564, 2020).
C1RL also shares sentences with these, for which no sentence is quoted: cervical cancer (1 paper); dysphoria (1); meningitis (1); non-Hodgkin lymphoma (1); preeclampsia (1); renal cell cancer (1); Sepsis (1).